LINC00378 (long independently transcribed non-coding RNA 378)
Gene: Long non-coding RNA gene on chromosome 13 (60,618,983 to 61,176,809, forward strand). Ensembl gene ENSG00000225249.
Diseases named in the same sentence as LINC00378 in open-access papers:
LINC00378 is named in the same sentence as 1 disease in open-access papers, as found by Europe PMC text mining. Sharing a sentence is not in itself a finding about the gene and the disease. The quoted sentences say what the papers report.
Sepsis (1 paper, 2022). Sepsis is defined as life-threatening organ dysfunction caused by a dysregulated host response to infection. "Our findings revealed three novel low-frequency variants associated with reduced 28-day survival among sepsis patients: one in SAMD9 (the p.Ala1556Thr exonic variant), one intergenic to SLC5A12\FIBIN, and another intergenic to LINC00378\MIR3169." (PMID 36335405, 2022).